LAPTM4B (lysosomal protein transmembrane 4 beta)
Diseases named in the same sentence as LAPTM4B in open-access papers (continued):
Sharing a sentence is not in itself a finding about the gene and the disease.
renal carcinoma (1 paper, 2023). A carcinoma arising from the epithelium of the renal parenchyma or the renal pelvis. "In conclusion, LAPTM4B is an adverse factor in the development of renal cancer." (PMID 36937841, 2023). "The data indicated that LAPTM4B contributes to the growth of renal cancer cells." (PMID 36937841, 2023). "In the results of immune infiltration, we observed that expression of LAPTM4B is positively correlated with CD8 T cells, and is lower in high-grade renal cancer than in early-stage renal cancer, possibly explaining the poor response to treatment in advanced renal cancer." (PMID 36937841, 2023). "Our results showed that LAPTM4B is highly expressed in Fuhrman III/IV ccRCC tissues and are reduced in Fuhrman I/II ccRCC tissues, suggesting the phenomenon to possibly be related to the heterogeneity of renal cancer." (PMID 36937841, 2023). "The negative correlation between LAPTM4B and most immune checkpoints partially explained the insensitivity of ccRCC to immunotherapy, this evidence suggested that LAPTM4B may promote the growth and metastasis of renal cancer by boosting the immune escape of tumor cells." (PMID 36937841, 2023).
Salmonella Infections (1 paper, 2018). Infections with bacteria of the genus SALMONELLA. "On the other hand, FOXO signaling (TNFSF10, PRKAB1, GADD45B, STK4, STAT3), Salmonella infection (ARPC2, ARPC5L, CCL3L3, CCL4) and lysosome (LAPTM4B, HGSNAT, CD164, ATP6V0A2) pathways were up-regulated, albeit weakly, in the HLA-DR- Teff subset." (PMID 30231065, 2018).
sarcoma (1 paper, 2023). A usually aggressive malignant neoplasm of the soft tissue or bone. "Combined analysis from TCGA and GTEx databases indicated that LAPTM4B expression negatively correlates with overall survival expectation in both sarcoma and pan-cancer including 33 types of cancer." (PMID 37147294, 2023). "In order to assess the functional roles of LAPTM4B in OS, we first mined the Cancer Cell Line Encyclopedia (CCLE) database and found LAPTM4B expression in sarcoma is relatively high among other cells." (PMID 37147294, 2023).
cancer (49 papers, 2007 to 2026). A tumor composed of atypical neoplastic, often pleomorphic cells that invade other tissues. "LAPTM4B has been implicated in tumor progression 11-17 and metabolic reprogramming 23-26 across multiple cancer types." (PMID 41362742, 2026). "We identified that LAPTM4B expression was increased in various cancers, with significant associations with clinical outcomes." (PMID 40092987, 2025). "We determined the expression levels of LATPM4B mRNA in various cancers, and confirmed the most common types of LAPTM4B mutations and their locations." (PMID 40092987, 2025). "We associated LAPTM4B expression levels with tumor microenvironment and the infiltration levels of immune cells and genes in various cancers." (PMID 40092987, 2025). "We also assessed the diagnostic, prognostic and therapeutic values of LAPTM4B expression across cancers and differentiated its expression levels across several immune and cellular subtypes of cancers." (PMID 40092987, 2025). "Overall, we found that LAPTM4B expression was associated with immune subtypes in 19 cancer types and correlated with molecular subtypes in 14 cancer types." (PMID 40092987, 2025). "Studies have shown that LAPTM4B is overexpressed in a variety of cancers, in which the genetic polymorphism of LAPTM4B is associated with tumor susceptibility." (PMID 40231269, 2025). "A total of 17 types of cancer had high diagnostic accuracy (AUC >0.9), suggesting that LAPTM4B had good diagnostic value." (PMID 40092987, 2025). "Lysosome Associated Protein Transmembrane 4B (LAPTM4B) is involved in biological processes critical to cancer progression, such as regulation of solute carrier transporter proteins and metabolic pathways, including mTORC1." (PMID 38902268, 2024). "The Sankey diagrams based on the top 15 enriched pathways further predicts the flows from key metabolites to the biological pathways, suggesting that LAPTM4B regulated metabolic pathways associate with several diseases, including cancer." (PMID 38902268, 2024). "The LAPTM4B gene has been found to be associated with cell proliferation, invasion, and metastasis in cancer, by blocking lysosomal degradation and by protecting cells from autophagy." (PMID 33751844, 2021). "The Spearman analysis also revealed a positive linear association among HIF-1α, MDR1 and LAPTM4B in all the studied cancer patients." (PMID 30746305, 2019). "Overexpression of HIF-1α, MDR1 and LAPTM4B has been associated with poor disease outcome in many cancers when studied individually at tissue level." (PMID 30746305, 2019). "With reference to LAPTM4B, it has been extensively studied for genotyping studies associated with various cancers from serum as well as investigated for its expression in PBMCs and platelets." (PMID 30746305, 2019). "Preceding studies have examined the possible link between LAPTM4B polymorphism and susceptibility to several cancers, but the findings are still inconsistent." (PMID 30255662, 2018). "In the current study, we performed a meta‐analysis to find out the exact role of LAPTM4B polymorphism on risk of cancer." (PMID 30255662, 2018). "The results revealed that LAPTM4B polymorphism significantly increased the risk of cancer in codominant, dominant, overdominant, and allele genetic inheritance models." (PMID 30255662, 2018). "Another meta-analysis for the estimation of association between LAPTM4B expression and cancer prognosis was conducted." (PMID 25932367, 2015). "More studies on the association of LAPTM4B polymorphisms and cancer risk in other countries are warranted to confirm the association." (PMID 25932367, 2015). "Mounting evidences show that overexpression of LAPTM4B-35 is associated with a poor prognosis and contributes to cellular transformation, tumorgenesis, and metastatic progression in several human cancers." (PMID 25714029, 2015). "Accumulated studies have been conducted to determine the association of LAPTM4B polymorphism with cancer risk." (PMID 25932367, 2015).
cancer (continued). "In our meta-analysis, the association between LATPM4B polymorphism and cancer susceptibility and the association between LAPTM4B expression levels and cancer prognosis were observed in multiple cancers." (PMID 25932367, 2015). "LAPTM4B has been studied mainly in human and specifically in regard to its association with various carcinomas, as referenced above." (PMID 25881887, 2015). "Previous studies revealed that LAPTM4B polymorphisms contribute to the risk of certain types of cancers." (PMID 22984585, 2012). "Lysosomal protein transmembrane 4 beta (LAPTM4B) is a novel cancer-related gene which has two alleles designated LAPTM4B*1 and LAPTM4B*2." (PMID 22984631, 2012). "It is possible that filopodia growth contributes to the increased invasive potential and metastasis associated with LAPTM4b overexpressing cancers and cells." (PMID 22096579, 2011). "Furthermore, LAPTM4B has been implicated in enhancing cancer cell stemness 14,17, facilitating autophagy 18, and conferring resistance to chemotherapeutic agents 19,20." (PMID 41362742, 2026). "Moreover, we found 34 mutation sites between amino acids 0 and 317, including 24 missense mutations, 2 truncating, 8 SV/fusion, and S265N as the most frequent mutation sites within LAPTM4B across cancers." (PMID 40092987, 2025). "Previous studies have implicated LAPTM4B in regulating autophagy in cancer contexts." (PMID 39147759, 2024). "Lysosomal-associated protein transmembrane-4 beta (LAPTM4B), a novel oncogene, promotes tumorigenesis and may be a potential prognostic biomarker in several cancers." (PMID 30940109, 2019). "Hence, the present meta‐analysis was designed to investigate the impact of LAPTM4B polymorphism on risk of cancer." (PMID 30255662, 2018). "Previous studies have shown that LAPTM4B allele*2 was a susceptibility factor for various cancers; however, the reason for this susceptibility is still unknown." (PMID 29337428, 2018). "In conclusion, the finding of this meta‐analysis illustrated that LAPTM4B polymorphism may affect the risk of development of cancers." (PMID 30255662, 2018). "The elevated LAPTM4B-35 expression was associated with cancer recurrence (P = 0.031)." (PMID 27486880, 2016). "LAPTM4B-35 overexpression causes carcinogenesis and enhances cancer growth, metastasis and multidrug resistance, and thus may be a candidate for therapeutic targeting." (PMID 27542271, 2016). "To evaluate the association of LAPTM4B polymorphisms and the risk of cancer development, we conducted a meta-analysis of 18 enrolled case–control studies including gynecological tumors, digestive system cancers, lung cancer, breast cancer, nasopharyngeal carcinoma, and lymphoma." (PMID 25932367, 2015). "While the results of the studies concerning the relationship between LAPTM4B polymorphism and cancer risk are inconsistent, we conducted this meta-analysis to determine the strength of the association with a relatively large sample size containing 4556 cases and 4584 controls." (PMID 25932367, 2015). "In conclusion, LAPTM4B polymorphism is associated with cancer risk and allele*2 is a risk factor." (PMID 25932367, 2015). "All above support our hypotheses of the association between LAPTM4B polymorphism and cancer susceptibility." (PMID 25932367, 2015). "LAPTM4B is a member of the lysosome-associated transmembrane protein superfamily that is differentially expressed in normal human tissues and upregulated in various types of carcinomas." (PMID 25881887, 2015). "Distribution of LAPTM4B alleles in cancer cases and controls." (PMID 22984585, 2012). "To elucidate potential associations between LAPTM4B and intracellular epigenetic alterations, we examined the status of genomic methylation and the expression of genes involved in mRNA methylation in various types of cancer cells using data from cBioPortal database." (PMID 40092987, 2025). "Collectively, these findings underscore multifaceted role of LAPTM4B in tumorigenesis and cancer progression." (PMID 41362742, 2026).
cancer (continued). "To explore the relationship between LAPTM4B expression and immune status in pan-cancer, we conducted a correlation analysis." (PMID 40092987, 2025). "Our result revealed that LAPTM4B was associated with CD8+ T cells, macrophages M2 and Tregs in many cancers, which suggested that high LAPTM4B expression had inhibitory immune microenvironment." (PMID 40092987, 2025). "Moreover, we also found that LAPTM4B was positively correlated with RNAss and DNAss across most of the cancers, which indicates that high expression of LAPTM4B might be associated with cancer tumor recurrence and metastasis." (PMID 40092987, 2025). "In this study, we aimed to elucidate the expression, clinical characteristics and immunological characteristics of LAPTM4B across various cancers." (PMID 40092987, 2025). "In recent years, there has been remarkable progress in research on LAPTM4B in cancer chemotherapy resistance, revealing its complex and multifaceted mechanism of action." (PMID 40231269, 2025). "And we found that LAPTM4B expression was significantly related to DNA methylation and RNA modifications in these cancers." (PMID 40092987, 2025). "Understanding the role of LAPTM4B in different types of cancer is essential to develop targeted therapies." (PMID 40231269, 2025). "Tumor growth and sensitivity to chemotherapy can be modified by altering LAPTM4B expression, making it a promising target for innovative cancer therapies." (PMID 40231269, 2025). "In order to examine the expression profile of LAPTM4B in pan-cancers, we evaluated its expression across 34 cancer types using data from TCGA, TARGET, and GTEx databases." (PMID 40092987, 2025). "In summary, our study systematically performed a comprehensive pan-cancer analysis of LAPTM4B, and explored the expression, immunological features, and functions of the LAPTM4B gene in the Ph+ B-ALL mouse model." (PMID 40092987, 2025). "LAPTM4B promotes drug release through the efflux pump P-gp, which stimulates multi-drug resistance in cancer cells." (PMID 40231269, 2025). "A study reported the design and synthesis of the far infrared/near infrared (FR/NIR) fluorescent lamp probe DBT-2EEGIHGHHIISVG, which specifically displays the LAPTM4B protein in cancer cells and tumor-bearing mice." (PMID 40231269, 2025). "Most studies on LAPTM4B have primarily focused on intracellular signaling in certain types of cancers, and a comprehensive understanding of LAPTM4B in tumorigenesis is still lacking." (PMID 40092987, 2025). "LAPTM4B is required for lysosomes function, participates in the cell death program, promotes autophagy and tolerance to metabolic stress in cancer cells, and is an essential gene for adjuvant drug resistance." (PMID 40092987, 2025). "To evaluate the clinical significance of elevated LAPTM4B expression in various cancers, we conducted a Cox proportional hazards model analysis encompassing OS, DSS, DFI, and PFI." (PMID 40092987, 2025). "The upregulation or mutation of LAPTM4B and EGFR in a variety of cancers has attracted much attention because of their association with cancer cell proliferation, survival, drug resistance, and poor prognosis." (PMID 40231269, 2025). "Expression of LAPTM4B reduces the output of advanced endosomal ceramide and promotes apoptosis in cancer cells." (PMID 40231269, 2025). "Subsequently, the correlations of expression levels between LAPTM4B and immune checkpoint genes and immune regulatory genes in cancers were also investigated." (PMID 40092987, 2025). "To generalize the potential impact of our findings, we profiled LAPTM4B regulation of the soluble metabolome in three cancer cell lines." (PMID 38902268, 2024). "LAPTM4B is regarded as an oncogenic protein as it is overexpressed in many human cancers and correlates with poor prognosis." (PMID 37759697, 2023).
cancer (continued). "G6PD is mainly expressed in TAMs, LAPTM4B is predominantly expressed in tumor endothelial cells (TECs), GBA is expressed in both cell populations, and TRAF5 is primarily expressed in cancer-associated fibroblasts (CAFs)." (PMID 38170006, 2023). "LAPTM4B promoted cancer cell proliferation via the PI3K/AKT signaling pathway and mediated EGFR family-promoted autophagy." (PMID 36076996, 2022). "Lysosomal protein transmembrane 4 beta (LAPTM4B) is upregulated in many types of cancers, is necessary for cancer cell proliferation, and confers anti-cancer drug resistance." (PMID 36076996, 2022). "Consecutively, studies have confirmed that LAPTM4B is abnormally expressed in different malignant solid tumors and plays a role in cancer promotion." (PMID 32651973, 2021). "In the available studies, it has been demonstrated that LAPTM4B can promote EGFR signaling in cancer cells and is essential in the process of autophagy triggered by inactive EGFR." (PMID 32651973, 2021). "LAPTM4B upregulation has been observed in various cancers, including hepatocellular carcinoma, breast cancer, and lung adenocarcinoma." (PMID 32340207, 2020). "In case of LAPTM4B, there was 13–14 fold increase in expression of LAPTM4B in all cancer samples compared to normal healthy controls." (PMID 30746305, 2019). "The elevated expression of HIF-1α, MDR1 and LAPTM4B in peripheral blood of solid tumor patients can be a predictor of metastasis, disease progression and treatment response in these cancers." (PMID 30746305, 2019). "Previous literature suggests that LAPTM4B aids cancer cells towards survival advantage by promoting resistance to hypoxic microenvironment, nutrient deprivation and genotoxic stress contemplated by chemotherapy (Dielschneider, Henson & Gibson, 2017)." (PMID 30746305, 2019). "The high level of LAPTM4B expression was observed in the breast (2.703 ± 0.1312), ovarian (2.849 ± 0.1501), prostate (2.567 ± 0.1786) and colon (2.688 ± 0.1949) cancer patients compared to healthy controls (0.2546 ± 0.09648)." (PMID 30746305, 2019). "The positive correlation among all the studied cancers suggest similar upregulation of LAPTM4B leading to increased HIF-1α and MDR1 genes." (PMID 30746305, 2019). "The expression of HIF-1α, MDR1 and LAPTM4B in individual cancers has been well reported and related to cancer progression and metastasis at tissue level however in isolated studies." (PMID 30746305, 2019). "The majority of these results came from studies conducted in Hela cells, and the role of LAPTM4b for mTORC1 activity was confirmed in MDA-MB-231 (breast) or HEPG2 (liver) cancer cells." (PMID 30103560, 2018). "Although a series of clinical experiments have shown that various kinds of carcinomas with LAPTM4B‐35 overexpression present more invasive characteristics, the mechanism of the effect of LAPTM4B on migration and invasion is still unclear." (PMID 29337428, 2018). "ETS is therefore a candidate for treatment of HCC and some other cancers in which LAPTM4B-35 overexpresses." (PMID 27542271, 2016). "The utility of DBT-2EEGIHGHHIISVG in targeted imaging of LAPTM4B protein in cancer cells was investigated with confocal laser scanning microscopy." (PMID 26984064, 2016). "Cellular studies using HepG2 cancer cells, hepatic L02 cells and smooth muscle cells reveal that DBT-2EEGIHGHHIISVG is a safe probe for targeted LAPTM4B protein imaging in cancer cells." (PMID 26984064, 2016). "It is found that DBT-2EEGIHGHHIISVG can achieve targeted imaging of LAPTM4B proteins in HepG2 cancer cells and visualize LAPTM4B protein-expressed tumour tissues of live mice in a selective and high-contrast manner." (PMID 26984064, 2016). "In summary, we report the design and synthesis of an FR/NIR fluorescence light-up probe that can specifically detect and image LAPTM4B proteins in HepG2 cancer cells and in HepG2 tumour-bearing live mice." (PMID 26984064, 2016).